CD46 (CD46 molecule)
Diseases named in the same sentence as CD46 in open-access papers (continued):
Sharing a sentence is not in itself a finding about the gene and the disease.
breast carcinoma (continued). "Based on their involvement in breast cancer and the availability of commercial antibodies, the ADIPOR1, ADORA1, BTG2 and CD46 genes were selected among the 27 previously identified genes to further investigate the association of protein expression levels to overall patient survival." (PMID 20553615, 2010). "Importantly, CD46 and DGS2 are overexpressed in cancer tissues, including breast cancer." (PMID 38675909, 2024). "Similarly, breast carcinoma cells were more easily lysed after treatment with anti-CD59 and anti-CD55 antibodies, but a much higher degree of lysis was achieved when a mixture of anti-CD59, anti-CD55, and anti-CD46 antibodies was used." (PMID 35227072, 2022). "Before investigating the antitumor activity of CRAd-synNotch and ADX730 in T24 (MIBC) and BT474 (a COX-2 negative human breast cancer cell line) cells, we confirmed the expressions of CAR, CD46 and CD44 expressions on the cell surface." (PMID 40011711, 2025).
myeloma (16 papers, 2018 to 2025). "The gene encoding for CD46 is amplified on chromosome 1q in the majority of relapsed myeloma patients, as well as cells containing stem-like aldehyde dehydrogenase activity." (PMID 38001595, 2023). "The potential of therapeutic targeting using the CD46-ADC was demonstrated preclinically by its inhibition of myeloma cell proliferation in an orthometastatic xenograft (mouse) model." (PMID 40309774, 2025). "The change in the number of multiple myeloma cells with high or low CD46 were measured in each drug treatment well relative to matched populations in untreated wells." (PMID 39699274, 2025). "Since then many studies have documented CD46 upregulation in multiple myeloma (MM) and in a host of solid tumors, including ovarian, breast, cervical, colorectal, prostate, bladder, and others." (PMID 40309774, 2025). "By flow cytometry, CD45-negative multiple myeloma cells had bimodal CD46 expression, which was used to stratify all multiple myeloma cells into high or low CD46." (PMID 39699274, 2025). "An antibody–drug conjugate (ADC) targeting CD46 conjugated to monomethyl auristatin has a potent anti-myeloma effect in cell lines in vitro and in vivo, and patient samples treated ex vivo." (PMID 38001595, 2023). "To conduct an in vivo study of CD46–ADC on stem-like subpopulations of myeloma cells, we first piloted a PDX model of MM with human fetal bone grafts." (PMID 38001595, 2023). "For example, CD46 is usually overexpressed in tumors such as hepatocellular carcinoma, multiple myelomas, and bladder and colon cancers." (PMID 36575233, 2022). "Our results show that MeV-Stealth effectively targets and lyses CD46-expressing cancer cells in mouse models of ovarian cancer and myeloma, and evades inhibition by human measles-immune serum." (PMID 33534834, 2021). "By fully-retargeting the new envelope to the receptor CD46, we found that in mouse models of ovarian cancer and myeloma MeV-Stealth displayed oncolytic properties similar to the parental MeV vaccine." (PMID 33534834, 2021). "A receptor binding affinity of ~20 nM was required to trigger CD46-dependent intercellular fusion at levels comparable to the original MeV H/F complex and to achieve similar antitumor efficacy in myeloma and ovarian tumor-bearing mice models." (PMID 33534834, 2021). "Another study determined that in primary myeloma cells derived from bone marrow aspirates, a macropinocytosing CD46-antibody drug conjugate induced apoptosis and cell death but did not affect the viability of nontumor mononuclear cells." (PMID 33147799, 2020). "The potential of the CD46-ADC approach was demonstrated in MM in which potent inhibition of myeloma cell proliferation was achieved in an orthostatic xenograft (mouse) model." (PMID 33147799, 2020). "The region on chromosome 1q carrying CD46 commonly undergoes genomic amplification in relapsed myeloma patients." (PMID 33147799, 2020). "We next tested CD46–ADC for the ability to prevent primary myeloma cell regeneration and expansion." (PMID 38001595, 2023). "We conclude from this set of experiments that CD46 targeting drives oncolyis in both a xenograft myeloma model and an orthotropic model of ovarian cancer, and that exchange of the MeV coat by the homologous CDV-H/F fusion apparatus shields MeV from MeV-immune human serum." (PMID 33534834, 2021). "Notably, CD46 expression is increased up to 14-fold in relapsed multiple myeloma (MM) patients who have the region on chromosome 1q carrying CD46 genomically amplified (mean antigen density 313,190 for MM vs. 22,475 for healthy donor plasma cells)." (PMID 33147799, 2020). "CD46 was identified as the most differentially expressed marker in our flow cytometry panel, as it had higher expression in IGH-multiple myeloma (l2FC = 0.44, P = 5.76 × 10−7)." (PMID 39699274, 2025).
myeloma (continued). "The CD46 low cells, roughly equated to the LCE-multiple myeloma subpopulations, showed intrinsic resistance to the IMiDs, but remained sensitive to proteosome inhibitors and daratumumab." (PMID 39699274, 2025). "In contrast, therapeutic suppression of CD46 expression and inhibition of CD59 by specific peptides render multiple myeloma treatment with daratumumab and isatuximab far more effective." (PMID 39599800, 2024). "One study already demonstrated a role for CD46 and CD59 upregulation in human multiple myeloma, which limits the efficacy of immunotherapy by isatuximab." (PMID 39599800, 2024). "By establishing CD46 as an effective ADC target for preventing primary MM cell engraftment, we further support the notion that CD46 is an emerging target in multiple myeloma worthy of continued study." (PMID 38001595, 2023). "With ovarian cancer and myeloma as our targets, we ablated known receptor tropisms from CDV envelope glycoproteins and engineered them to display a single-chain variable fragment (scFv) with specificity for CD46." (PMID 33534834, 2021). "In summary, the data presented in this manuscript indicate that substitution of the MeV envelope glycoproteins by CD46-targeted CDV envelope glycoproteins is an alternative strategy to circumvent the inhibition of MeV-immune serum and achieve oncolysis in multiple myeloma and ovarian cancer models." (PMID 33534834, 2021). "We evaluated whether or not CD46 is highly expressed on myeloma cells that are phenotypically “stem-like”." (PMID 38001595, 2023). "Notably, across these lines we detected almost all of the major immunotherapy targets in myeloma, as well as canonical flow cytometry markers for plasma cells: BCMA, CD138/SDC1, CD38, CD56, SLAMF7/CS-1, CD46, Integrin-b7 (ITGB7), CD74/HLA-DR, TACI, CD48/SLAMF2, and LY9/CD229." (PMID 35840578, 2022). "ADCs targeting BCMA, CD38, CD46, CD56, CD74, CD138 are not discussed here since this special issue contains another article devoted to ADCs in multiple myeloma, and these targets are mainly explored in this disease setting." (PMID 36654819, 2022). "We treated several human myeloma cell lines and non-myeloma cell lines with BVDV to evaluate the expression of CD46 and to study the effect on cell viability by flow cytometry." (PMID 32653014, 2020).
atypical hemolytic-uremic syndrome (15 papers, 2011 to 2026). "Our search for syndromes with both tCHI and CHB revealed a maternal CD46 missense variant, recently reclassified from likely pathogenic to likely benign with respect to atypical hemolytic uremic syndrome." (PMID 34838142, 2021). "In general, heterozygous CD46 polymorphisms are associated with both atypical hemolytic uremic syndrome and hemolytic uremic syndrome, but have also been linked to spontaneous miscarriages and to preeclampsia in patients with autoimmune diseases." (PMID 34838142, 2021). "Mutations in CD46 predispose to atypical hemolytic uremic syndrome (aHUS) with low penetrance." (PMID 37477760, 2023). "Mutations in membrane cofactor protein (MCP; CD46) may predispose to the development of atypical hemolytic uremic syndrome (a-HUS)." (PMID 35160072, 2022). "In addition to C3GP, AP abnormality is also implicated in thrombotic microangiopathy (TMA), including atypical hemolytic uremic syndrome (aHUS), as suggested by mutations in C3, CFI, CD46, and CFH found in patients with aHUS." (PMID 34149444, 2021). "List of CD46 rare variants (RVs; variants with minor allele frequency < 0.001 in 1000 Genomes and ExAC databases and with CADD phred score ≥10) identified in 485 atypical hemolytic uremic syndrome (aHUS) patients recruited through the International Registry of HUS/TTP." (PMID 33224962, 2020).
ovarian carcinoma (15 papers, 2005 to 2024). A malignant neoplasm originating from the surface ovarian epithelium. "CD46 and Nectin-4 have been reported to be highly expressed on the surface of ovarian cancer cells, and MV has displayed a remarkable antitumor effect in a mouse model of ovarian cancer." (PMID 38606099, 2024). "The cultured M4 ovarian cancer cells and secondary M4 human ovarian cancer cells from BALB/c nude mice exhibited high homogeneity with a significantly higher CD46 expression ratio compared with the primary M4 ovarian cancer cells." (PMID 37621847, 2023). "The results indicated strong CD46 expression in primary M4 ovarian cancer cells, cultured M4 ovarian cancer cells, and secondary M4 human ovarian cancer cells isolated from the tumor of BALB/c nude mice at a high and stable rate." (PMID 37621847, 2023). "In ovarian cancer, the neutralization of CD46, CD55, and CD59 in combination with the anti-HER2 monoclonal antibodies trastuzumab and pertuzumab induces tumor cell killing in vitro." (PMID 34359708, 2021). "These four ovarian carcinoma cell lines highly expressed CD46, a major receptor for the Ad3 serotype." (PMID 31944306, 2020). "The oncolytic measles virus (MV-NIS), which uses the surface receptor CD46 for entry into cells is being trialled to treat drug resistant ovarian cancer in which CD46 is overexpressed." (PMID 32937961, 2020). "As an example, comparisons between CD46 and CAR-targeted adenoviral therapy have demonstrated superior outcomes with CD46 targeting in bladder cancer and ovarian cancer, despite comparable receptor expression by the tumor cells." (PMID 33147799, 2020). "CD46 has been shown to be highly expressed on colorectal, breast, prostate, lung, liver, and ovarian carcinoma cancer cells." (PMID 30319647, 2018). "Expression profiles of the native Ad5 receptor CAR and the Ad35 receptor CD46 were characterized on primary EOC cells cultured from the ascites of seven ovarian cancer patients." (PMID 27229159, 2016). "The immunoblotting experiments showed that the cultured ovarian cancer cells can shed the C regulators CD46, CD55 and CD59 into the culture medium." (PMID 15726105, 2005). "Ovarian cancer is one of the tumors expressing CD46 protein on the tumor cell surface." (PMID 37621847, 2023). "High CD46 expression may serve as a target for oncolytic viruses, with in-vitro studies showing promise with intraperitoneal application in ovarian cancer." (PMID 33415077, 2020). "We therefore propose selective transduction of CD46 over-expressing EOCs using re-targeted, Ad35-pseudotyped Ad vectors may represent a promising virotherapy for ovarian cancer." (PMID 27229159, 2016). "However, CD46 expression was constitutively high on EOC cells derived from all seven ovarian cancer patients in our cohort." (PMID 27229159, 2016). "In our study, both primary and secondary M4 ovarian cancer cells isolated and cultured from the patient's tumor and BALB/c nude mice bearing the M4 cell line exhibited high and stable CD46 expression." (PMID 37621847, 2023). "Membrane-bound CRPs (mCRPs), such as CD46, CD55, and CD59, are expressed by ovarian cancer tumors and cell lines." (PMID 34359708, 2021). "CD46 is often located within tight junctions and less accessible than DSG2 in many cells, including ovarian cancer." (PMID 31944306, 2020). "Most epithelial ovarian cancer (EOC) samples from a primary laparotomy and secondary cytoreduction procedures stained positive for CD46 (60% and 70%, respectively)." (PMID 31944306, 2020). "We therefore evaluated in vitro the relative transduction of epithelial ovarian cancers (EOCs) by Ad5 (via CAR) and Ad5 pseudotyped with the fiber of Ad35 (Ad5T*F35++) via CD46." (PMID 27229159, 2016). "To investigate whether the tumour cells' relative resistance to C could be due to the expression of membrane regulators CD46, CD55 and CD59, we performed immunohistochemical analysis of tumour cells isolated from two patients with ovarian cancer." (PMID 15726105, 2005).
ovarian carcinoma (continued). "The vector, named ONCOS-102, demonstrated effective oncolysis of several ovarian cancer cell lines, while in the absence of DSG-2, despite the presence of CD46 and CAR, no oncolysis was observed." (PMID 32957644, 2020).
colon carcinoma (14 papers, 2008 to 2024). "Our validation showed that the key AS of CD46 in colon cancer cells can contribute to T cell-mediated tumour cell killing." (PMID 35692800, 2022). "In spite of these disadvantages, targeting CD46 instead of CAR with a chimeric HAdV-C5 which contained the fiber of HAdV-B35 enhanced killing of CD46 expressing colon cancer cells and bladder cancer cells, both in vitro and in in vivo mouse models." (PMID 32957644, 2020). "In a recent follow-up study, MV-CD46-muPA has been developed, which was shown to target both human CD46-positive colon tumor cells and murine uPAR-expressing CAFs in vitro and in vivo." (PMID 33167307, 2020). "We have previously shown that CD46 is highly expressed in cancers that originate from the colon and the prostate, being overexpressed in almost 60% of colon cancers." (PMID 30201920, 2018). "In fact, we have previously shown that in colon cancer cells, CD46 effectively mediated gene transduction of an Ad5 fiber chimeric virus modified to contain the fiber knob from species B Ad35." (PMID 30201920, 2018). "It has been reported that CD46 expression was significantly higher in colon cancer tissues compared with adjacent normal colon tissues." (PMID 27203670, 2016). "In order to show that CD46 plays decisive role in species B adenoviral gene therapy for CD46-overexpressing colon cancers, we developed chimeric Ad5/35 vectors with fiber knobs from Ad35 to specifically target CD46 in cancer cells." (PMID 27203670, 2016). "The same phenomenon was confirmed in various colon cancer cells, where CD46 expression levels were found to correlate with viral gene transduction and cytotoxic effects." (PMID 27203670, 2016). "CD46 expression in both prostate and colon cancers is significantly higher than tumors from other origins (Q=56.85 with 7df, p<0.0001 Cochran-Mantel-Haenszel statistics based on Row Mean Scores Differ)." (PMID 27203670, 2016). "Western blotting revealed that CD46 was expressed in liver, breast, lung, kidney and colon cancer as well as the adjacent normal tissues." (PMID 24297460, 2014). "All colon carcinoma cells tested in the present study expressed higher amounts of CD46 than did A549 cells." (PMID 21455297, 2011). "Taken together, these results also indicate that the amounts of CD46 molecules, αvβ3 and αvβ5 integrins on the different colon carcinoma cells play decisively important role for RCAd11pGFP to enable internalization." (PMID 21455297, 2011). "To better define the expression of CD46 in primary and metastatic colon cancer, we examined colon cancer material, normal liver tissue and normal colon tissue for CD46 expression by immunohistochemistry (IHC)." (PMID 18560559, 2008). "CD46 has been reported to play an important role in immune evasion, and our bioinformatic analysis also indicates that CD46 can regulate T cell responses in colon cancer." (PMID 35692800, 2022). "In addition, CD46 expression was inversely correlated with the malignancy of colorectal cancers in colon cancers." (PMID 30201920, 2018). "Thus, while CD46 was ubiquitously expressed in all five colon cancer cells used in this study, more efficient Ad5/35-mediated gene transduction was achieved in HCT-116, DLD-1, and Caco-2 cells compared to HT-29 and SW620 cells." (PMID 27203670, 2016). "Flow-cytometric analysis of the immunofluorescence staining showed that in general, all colon carcinoma cell lines studied had a higher level of CD46 expression than A549 cells, but expression levels of the internalization receptors, integrins αυβ3 and αυβ5, were lower in comparison to A549 cells." (PMID 21455297, 2011). "However, the relationship between CD46 expression in colon cancer cells and the T cell response remains unclear." (PMID 35692800, 2022).
colon carcinoma (continued). "Although no complement regulator polymorphisms for risk of colon cancer have been identified, CD46, CD55, and CD59 were all upregulated in colon cancer compared to adjacent healthy tissue, with CD55 and CD59 expression correlating with tumor stage and differentiation level." (PMID 33362763, 2020). "Expression of CD46 is low in normal cells, but is upregulated in human cancer cells such as ovarian cancer, breast cancer, lymphoma, hepatocellular carcinoma, lung cancer, prostate cancer, and colon cancer, presumably to protect the cancer cells from the complement system." (PMID 30201920, 2018). "Interestingly, immunohistochemical studies staining for CD46 expression on excised colon cancer material, normal liver tissue and normal colon tissue revealed that strong CD46 staining was consistently seen in colon cancer tissue but was absent or weak in normal colon and liver tissue." (PMID 22312363, 2012). "To validate the role of CD46-9652-ES, we first investigated the expression levels of CD46△13 and CD4613+ in colon cancer and normal colon cell lines." (PMID 35692800, 2022). "It has been shown that expression levels of membrane-bound complement regulatory proteins (mCRPs), including CD46, CD55 and CD59, are considerably higher in colon cancer tissues than in normal neighboring normal colon tissues." (PMID 36612172, 2022). "We next investigated the CD46-9652-ES and PSMC5-43011-ES levels in 20 colon cancer samples characterized by CD4+/CD4- T cell infiltration and 20 colon cancer samples characterized by high/low M2 macrophage infiltration." (PMID 35692800, 2022). "First, high levels of CD46-9652-ES and PSMC5-43011-ES were proven in colon cancer." (PMID 35692800, 2022). "Additionally, the in vitro experiment validated that CD46-9652-ES and PSMC5-43011-ES are positively correlated with the infiltration of immune cells and promote the growth of colon cancer cells." (PMID 35692800, 2022). "Strong CD46 IHC staining was consistently seen in colon cancer tissue, but was absent or generally weak in normal colon and liver tissue." (PMID 18560559, 2008). "Similarly, as found for colon cancers, the overexpression of CD46 in bladder cancers implied a negative correlation with tumor stage, tumor grade, and the risk group with better survival." (PMID 30201920, 2018). "While CD46 was found to have no clinical relevance, levels of CD55 and CD59, other complement inhibitor membrane cofactor proteins, were positively correlated with the differentiation and tumor stage in colon cancers." (PMID 27203670, 2016).